MKI67 (marker of proliferation Ki-67)
Diseases named in the same sentence as MKI67 in open-access papers (continued):
Sharing a sentence is not in itself a finding about the gene and the disease.
cancer (continued). "There are highly mitotic/proliferative clusters (TOP2A, MKI67) of both LUAD and LUSC that may resemble highly aggressive and invasive cancer cells." (PMID 36368318, 2022). "MKI67 was also related to CD4+ T cell infiltration degrees in 22 cancers, CD8+ T cell infiltration degrees in 19 cancers, DC infiltration degrees in 25 cancers, neutrophil infiltration degrees in 24 cancers, and macrophage infiltration degrees in 17 cancers." (PMID 34724892, 2021). "Furthermore, Spearman correlation analysis in TCGA HCC tissues revealed that MARCH6 was positively correlated with MKI67, CTNNB1, CDH2, FN1 and WNTSA, which were demonstrated as oncogene in cancer growth and metastasis." (PMID 34273954, 2021). "3D cultured cells were also shown to have lower levels of genes related to cell proliferation or mitosis (CCNA2, MKI67, and BUB1) and differentiation (ESR1) relative 2D cultured, consistent with higher levels of a cell cycle inhibitor (CDKN1) and cancer stemness–related markers (CD44 and MALAT1)." (PMID 34869246, 2021). "Although proliferation of siRNA treated DLD-1 cells was not different, MKI67 expression faded in siRNA treated cancer cells." (PMID 34073605, 2021). "When the 16 cancer-related genes of the test were analyzed separately, the ESR1 transcript level was highly predictive of adjuvant tamoxifen benefit, while the MKI67 transcript level, encoding the Ki67 protein, was not." (PMID 30041599, 2018). "Furthermore, we have identified additional genes downregulated by Cl-amidine, including MKI67, MCM5, and MCM2, each with known functions in cancer progression." (PMID 23110523, 2012). "The results showed that MKI67 was significantly positively correlated with several of the pan-cancer immune checkpoint genes in some cancer types, such as THCA, STAD, LIHC, and BRCA, but also negatively correlated with the immune checkpoint genes in some cancer types, including THYM and GBM." (PMID 40070823, 2025). "Moreover, BIRC-5, KNTC-1, MCM2, MKI-67, PCNA, and E2F4 genes were downregulated in HCT-116 cancer cell lines, and there was no significant change in the expression of the same genes in HT-29 cancer cell lines." (PMID 40872562, 2025). "Lastly, KRT1high BLCA patients had significantly higher expression of EGFR and MKI67, suggesting that proliferation is potentiated in this group; this complements the survival analysis (high KRT1 is unfavorable in BLCA) and IHC data (KRT1 staining is higher in cancer than normal specimens)." (PMID 35361846, 2022). "Notably, TRPV1 expression had a negative correlation with the expression of MKI67, a marker for cell proliferation, in pan-cancer (p = 3.04 × 10−93; r = −0.28) and in five cancer types (p < 0.05)." (PMID 36304985, 2022). "In our research, we also detected that the high-M1/FRGPI group presented a higher MKI67 expression and enriched “cell cycle” and “DNA replication” gene sets, which meant that the high-M1/FRGPI group might have more aggressive cancer cells and advanced cell proliferation." (PMID 35368652, 2022). "MKI67 expression levels in cancer and noncarcinoma samples were studied." (PMID 34724892, 2021). "While a negative correlation between MKI67 expression and TMB and MSI in different cancer types, including THYM for TMB and SKCM, PCPG, and DLBC for MSI." (PMID 40070823, 2025). "Although there were few differences in gene expression in surviving cancer cells after Pembrolizumab treatment, PDS cultures not-responding to the treatment had significantly higher SOX2 and lower MKI67 expression compared to responding PDS cultures." (PMID 40240529, 2025). "TERT, MKI67, and MYC mRNA expression was higher in cancer tissues than in non-HCC liver samples." (PMID 22912812, 2012).
infection (344 papers, 2006 to 2026). The state of being infected such as from the introduction of a foreign agent such as serum, vaccine, antigenic substance or organism. "This is exemplified by the expression pattern of the proliferation markers Ki67 (Mki67), Pcna, Ccna2 and the minichromosome maintenance complex genes Mcm2 and Mcm6, which peak late in infection (Cell Cycle panel)." (PMID 38107402, 2023). "Of note, these cell types with the highest frequency of cell communication among AT2/AT1 cells were MKI67+, End and basal cells in the healthy group, but the infection group was Macro, Neu, and Mono cells." (PMID 37087411, 2023). "Consistent with an important role for IL22 in epithelial barrier repair in the bladder, we observed fewer Ki67-positive cells within the bladder epithelium in IL22ra1−/− mice at 24 h following infection as well as a reduction in Mki67 transcripts." (PMID 35845169, 2022). "IFNγ exposure reduced mean MCM2 and MKI67 transcript expression in BKPyV-infected cultures compared with infection alone but, due to the variance in the IFNγ-response, these changes were not statistically significant." (PMID 35194151, 2022). "We found that interferon controls the infection and that astrovirus infects all major cell types and lineages and induces expression of the cell proliferation marker MKI67." (PMID 34309190, 2021). "Cluster 1 was more heterogenous and lacked a distinct transcriptional profile, whereas Type I IFN (Isg15, Ifi206, Ifit3, Ccl5) and proliferative signatures (Cdk1, Mki67, Tuba1b) were observed in clusters 3 and 5, respectively, whose numbers remained stable between days 7 and 14 after infection." (PMID 39989461, 2025). "Besides cell death-related genes, Mki67 was also upregulated in virus-positive AM-Cd36 cells, and consequently, we identified a proliferating AM-Cd36 subpopulation termed as AM-Cd36-Mki67 (cluster 19) at d2, the early stage of infection." (PMID 39414783, 2024). "MKI67 was measured by flow cytometry and it was also overexpressed in SCs at 24 h post-infection." (PMID 37478057, 2023). "Further, we found 8.2% of actively proliferating hAT2 cells (MKi67+ h3ACs) in uninfected h3ACs (cluster 1), which was more or less maintained across infection progression in infected h3ACs (cluster 2, 10.6%; cluster 3, 12.8%; cluster 4, 3.6%; cluster 5, 30.3%; and cluster 6, 5.1%)." (PMID 33142113, 2020). "A group of Treg-signature genes (Areg, Arhpag20, Bub1b, Ccl12, Ccr5, Il1r1, Mki67 (Ki67) Ncf1, Nrp2, Tnfrsf9, Tcf19, Uhrf1, and Wnt3) were expressed at higher levels in IFNARfl/fl x Foxp3YFP-Cre mice than WT controls on day 5 Armstrong infection." (PMID 29672594, 2018). "In addition, microglia related genes, and genes associated with microglial cell activation (Mki67, Cd40, Tmem119 and Cx3cr1) were significantly induced 4 days following VACV-Wyeth infection indicating the possible role of these cells in the induction of immune response in the brain." (PMID 30759813, 2019). "Four genes (ASPM, CENPF, MKI67, and TOP2A), which are well documented as stem cell and cell proliferation markers, were overexpressed at 24 h post-infection." (PMID 37478057, 2023). "Comparative scRNA-seq analysis of ferret and human tissues revealed that the MKI67+ PB1 subset comprised the majority of SFTSV+ cells in both ferret groups and human fatal cases, with the highest per-cell viral UMI counts, highlighting its role as a major target for SFTSV infection and replication." (PMID 40794649, 2025).
breast (30 papers, 2012 to 2025). "Consequently, we selected eight statistically significant TACTs—EPCAM, KRT19, ERBB2, MKI67, MCAM, FOXA2, SNAI2, and NPTN—which we designated as colorectal TACTs (C-TACTs)." (PMID 40003943, 2025).
MKI67 also shares sentences with these, for which no sentence is quoted: lymphoma (192 papers); neuroendocrine carcinoma (187); meningioma (182); adenocarcinoma (167); invasive ductal carcinoma (143); invasive breast carcinoma (128); squamous cell carcinoma (98); carcinoids (74); pituitary adenomas (69); pancreatic neuroendocrine tumor (66); non-small cell lung carcinoma (62); astrocytomas (60); diffuse large B-cell lymphoma (44); oral squamous cell carcinoma (43); benign tumors (41); ovarian tumors (41); dysplasia (40); endometriosis (39); ameloblastoma (36); B-cell lymphoma (36); gastrointestinal stromal tumor (35); rectal cancer (33); small cell carcinoma (33); cyst (32); epithelial dysplasia (32); renal cell carcinoma (32); ductal carcinoma (31); papillary thyroid carcinoma (31); oral cancer (30); carcinoma in situ (28).
A further 981 diseases each share a sentence with MKI67 in 28 papers or fewer.